STAT3 (signal transducer and activator of transcription 3)
Diseases named in the same sentence as STAT3 in open-access papers (continued):
Sharing a sentence is not in itself a finding about the gene and the disease.
cancer (continued). "The IL6/JAK2/STAT3 pathway is key to tumorigenesis, progression, metastasis, and immune escape, and the transcription factor STAT3 controls how quickly cells grow, move, and spread in a number of different types of cancer." (PMID 40874680, 2025). "We speculate this time‐dependent effect may reflect the dual nature of STAT3 signaling, which is known to regulate proliferative pathways in cancers." (PMID 40492515, 2025). "As the pathway analysis identified the significant activation of the STAT3 signaling axis following cancer-driven immune education, we investigated whether STAT3 inhibition could reverse or suppress the functional consequences of this reprogramming." (PMID 41514627, 2025). "Importantly, VE-821 reversed cisplatin-induced activation of signal transducer and activator of transcription 3 (STAT3), a signaling molecule often involved in cancer survival, and further increased γ-H2AX levels, indicating enhanced DNA damage." (PMID 40869030, 2025). "Thus, all these data collectively indicate that B7‐H3 potentiates cancer cell stemness through c‐Met/STAT3 signaling." (PMID 40859957, 2025). "Additionally, Tregs upregulate PDL-1 expression in MSCs via the p-STAT3 pathway, promoting immune tolerance and accelerating cancer progression in GC patients." (PMID 40136652, 2025). "This inhibition could lead to a downstream suppression of STAT3 phosphorylation and activation, ultimately disrupting critical cancer-promoting signaling pathways." (PMID 40243485, 2025). "In addition to IFN-γ response-associated genes (JAK1, STAT1 and STAT3), CIITA, a master regulator of MHC-II gene expression, was highly expressed in MHC-II+ cancer cells." (PMID 41281745, 2025). "STAT3 is constitutively activated in multiple cancer types, such as HNSCC, breast cancer, lymphoma, melanoma, prostate cancer, and lung cancer, and plays an important role in tumorigenesis, progression, metastasis, and recurrence, resulting in poor clinical prognosis." (PMID 40242440, 2025). "Several STAT3 target genes promote a feedforward loop between normal and transformed cells, promoting cancer driving inflammation, angiogenesis, and metastasis, while disrupting cancer surveillance." (PMID 40723872, 2025). "We propose that the STAT3 transcriptional program operating in cancer cells enforces their malignant identity, rather than providing classical features of transformation, and shapes cancer persistence following KRAS inactivation." (PMID 40859018, 2025). "Mechanistic explorations revealed that ajuforrestin A could arrest A549 cells in the G0/G1 phase of the cell cycle, provoke apoptosis in cancer cells, and impede their migration by modulating the STAT3 and FAK signaling cascades." (PMID 40906092, 2025). "Furthermore, miR-30e-5p reduces tumorigenesis by targeting Sirt1/JAK/STAT3 signaling, which plays a critical role in cancer cell survival, proliferation and immune evasion." (PMID 40805201, 2025). "The constitutive and aberrant activation of c-MET mediated by NF-κB contribution provokes several downstream signaling pathways (MAPK, PI3K/AKT, STAT3) which subsequently promote cancer proliferation, survival, progression, angiogenesis, invasion and metastasis." (PMID 40022036, 2025). "Inhibiting these pathways can block STAT3 and slow cancer progression." (PMID 40407951, 2025). "The IL-6/JAK/STAT3 pathway is overactive in numerous cancer types." (PMID 40244228, 2025). "Through the control of numerous downward target genes, STAT3 may boost angiogenesis, support cancer cell growth and spread, suppress apoptosis, and encourage cellular growth and survivability." (PMID 40350446, 2025). "Additionally, the activation of STAT3, which is upregulated in cancer cells, has been shown to enhance DNA repair." (PMID 40915175, 2025). "One of APE1's targets, STAT3, coordinates the transcription of genes involved in cancer hallmarks." (PMID 41090323, 2025).
cancer (continued). "Intracellular and extracellular visfatin has been associated with cancer development by promoting cellular growth, angiogenesis, and metastasis through the MAPK, AKT, STAT3, and NF-κB/Notch1 pathways in macrophages, human endothelial cells, and breast cancer cells." (PMID 40040878, 2025). "Phytocompounds may target various deregulated signaling pathways, including NF-кB, PI3K/mTOR, MAPKs, AMPKs, TGF-β, Wnt/β-catenin and JNK/STAT3 pathways in various cancers." (PMID 40294146, 2025). "In the osteoblasts_Gapd2 subpopulation, pathways such as proteoglycans in cancer (Col1a1, Col1a2, Hcls1, Hif1a, Stat3, Vav1), IL-17 signaling (Mmp13, Mmp3, S100a9, Ccl7, Cebpb), and ECM–receptor interaction (Col11a2, Col1a1, Ibsp, and Tnn) were activated (p < 0.05)." (PMID 41459160, 2025). "For example, CCL5 derived from TAMs could promote prostate CSC self-renewal and cancer metastasis via activating β-catenin/STAT3 signaling." (PMID 39990669, 2025). "Different drug delivery platforms supporting STAT3 inhibitors in cancer therapy." (PMID 40166646, 2025). "Additionally, exposure to the tobacco-specific carcinogen NNK was found to induce miR-876 expression and STAT3 activation, implicating environmental factors in miR-876 regulation and promote cancer recurrent." (PMID 40140827, 2025). "Finally, we evaluated the effectiveness of STAT3 silencing as a result of siSTAT3 delivery by both types of spheres to the HER2+ cancer cells." (PMID 40584785, 2025). "Elevated levels of pro-inflammatory cytokines, such as IL-6 and TNF-α, which are commonly observed in cancer cachexia, trigger STAT3 activation, leading to the transcription of genes that exacerbate systemic inflammation, accelerate muscle protein degradation, and disrupt lipid metabolism." (PMID 40704145, 2025). "Moreover, recent research has shown that IL-6 secreted by adipocytes drives STAT3 signaling to induce HIF1α in cancer cells, with HIF1α known to regulate ANGPTL4 expression." (PMID 40616161, 2025). "However, in cancer, hyperphosphorylated STAT3 activates oncogenic transcription factors such c-Myc and Oct-4, leading to enhanced cell proliferation and survival, as well as aggressive cancer cell stemness." (PMID 40075607, 2025). "For cancer cells to multiply, the STAT3 protein must first be activated." (PMID 39898127, 2025). "Additionally, emerging investigations have shown that CRC-derived EVs carrying miR-181a-5p can trigger the activation of hepatic stellate cells (HSCs) into cancer-associated fibroblasts (CAFs) by targeting SOCS3 and stimulating the IL-6/STAT3 pathway." (PMID 40493409, 2025). "Thus, multiple pathways and their related transcriptional factors have been shown to regulate PD-L1 expression by STAT3 and thereby contribute to the evasion of cancer cells from the immune system." (PMID 40941018, 2025). "Some germacranes induce apoptosis in cancer cells by altering the redox balance and activating the mitochondrial pathway, as well as inhibiting NF-κB and signal transducer and activator of transcription 3 (STAT3), making them promising anti-cancer therapeutic tools." (PMID 41149747, 2025). "Additionally, the JAK2/STAT3 pathway can interact with other pathways, such as the NF-κB and FOXO pathways, which are closely associated with cancer development." (PMID 40978029, 2025). "Furthermore, the restoration of the STAT3 pathway through the addition of exogenous IL-6 supports the notion that MCL exerts its anti-cancer effects by downregulating IL-6, thereby blocking STAT3 activation." (PMID 40051564, 2025).
cancer (continued). "The stimulation of the IL-6/STAT3 pathway is intricately linked to the processes of EMT and the manifestation of stem cell-like traits, which ultimately contribute to adverse outcomes in various individuals diagnosed with cancer." (PMID 40497987, 2025). "However, in many cancers, the aberrant form of glycosylated IL-6 reduces STAT3 activation, leading to increased activity of the SRC-YAP-SOX2 signaling axis." (PMID 41376623, 2025). "STAT3 is, therefore, an attractive pathway for diverting inflammation in cancer treatments." (PMID 40420174, 2025). "Moreover, novel anti-cancer agents target STAT3, indicating their potent clinical benefits in anti-cancer therapy." (PMID 40004077, 2025). "Thus, focusing on the STAT3 pathway is a viable approach for creating new cancer medications because it stimulates the migration and invasion of cancer cells, prevents apoptosis, and promotes cell proliferation." (PMID 40943427, 2025). "However, STAT3 is constitutively active in many cancers, supporting cell proliferation, invasiveness, and the cancer stemness phenotype." (PMID 39985075, 2025). "Microgliosis triggered the activation of signal transducer and activator of transcription 3 (STAT3), which has been observed in both chronic illnesses and cancers of the periphery to promote proinflammatory responses that can result in degradation or phagocytosis of healthy, unaffected cells." (PMID 41141377, 2025). "Theoretically, AGEs increase oxidative stress and upregulate certain pro-carcinogenic transcription factors (NFkB and STAT3) and other signalling pathways such as the MAPK pathway by binding to the AGE receptor (RAGE) to form the AGE-RAGE complex, which would increase cancer risk." (PMID 40431378, 2025). "In addition, EZH2 can likewise take part in various molecular signaling pathways, like PI3K/Akt/mTOR and JAK2/STAT3, to promote the proliferation and migration of cancer cells." (PMID 41154714, 2025). "IRE1α/XBP1 axis regulates STAT3 signaling in skeletal muscle during cancer cachexia." (PMID 40655023, 2025). "Based on network pharmacology and molecular docking predictions identifying EGFR/STAT3 signaling as a potential key mechanism, we investigated whether curcumin modulates this pathway to affect cancer cell proliferation, apoptosis, invasion, and migration." (PMID 41312415, 2025). "Additionally, triptolide impedes muscle development and cell proliferation in zebrafish larvae by interfering with several signaling pathways, including Notch1 and STAT3, which are also involved in cancer cell regulation." (PMID 40490812, 2025). "Understanding the complex STAT3-AhR network in the regulation of chemical carcinogenesis could open new avenues for cancer prevention or treatment, particularly in personalized medicine, aiming to improve life expectancy and achieving a complete cure." (PMID 40141386, 2025). "Similarly, STAT3 mutations, the most common STAT mutations in cancer, are prevalent in hematologic tumors." (PMID 40362240, 2025). "For example, EVs from cancer-associated fibroblasts carry transcription factors like SNAI1/ZEB1 or miRNAs (e.g. miR-193a, miR-210 from bone marrow cells) that prime lung cells for invasiveness (via STAT3, Wnt, TGF-β pathways)." (PMID 41311647, 2025). "Advancing our understanding of STAT3-targeted interventions and translating these findings into clinical practice could significantly enhance quality of life and survival outcomes for cancer cachexia patients." (PMID 40704145, 2025). "CD44, a hyaluronic acid receptor, is a cancer stem cell marker and activates STAT3." (PMID 40683954, 2025).
cancer (continued). "Moreover, emerging data suggest a context-dependent crosstalk between SOX18 and the STAT3 signaling pathway, a key regulator of cancer cell survival, proliferation, and immune evasion." (PMID 41373817, 2025). "In addition, whereas cisplatin induces apoptosis primarily through DNA damage, APE inhibits cancer cell growth via a distinct mechanism involving G1 phase cell cycle arrest and suppression of the STAT3 signaling pathway." (PMID 40278288, 2025). "B7-H3 triggers different signaling cascades to activate downstream molecules that contribute to the malignant behavior of cancer cells, e.g., B7-H3 activates signaling pathways such as ERK, PI3K, and Stat3 in cancer cells, leading to accelerated cell proliferation and tumor growth." (PMID 40356928, 2025). "Natural compounds in ameliorating cancer cachexia via targeting STAT3 signaling." (PMID 40704145, 2025). "This complex interplay of epigenetic and transcriptional regulation highlights the central role of TKT in cancer metabolism, suggesting its potential as a therapeutic target, particularly in terms of inhibiting the STAT3-TKT signaling pathway and regulating TKT expression." (PMID 40230848, 2025). "This study identified a naturally occurring compound from C. lanceolatus which is known to have many biological properties that effectively binds to STAT3, inhibits its translocation and DNA binding, and ultimately prevents STAT3-dependent cancer transformation." (PMID 40061959, 2025). "STAT3 activation has been linked to the development of acquired drug resistance in various cancers, including triple‐negative breast cancer (TNBC)." (PMID 40860906, 2025). "As we know, STAT3 is a well‐known transcription factor with cancer‐promoting function." (PMID 40145330, 2025). "Signal transduction and transcription activator 3 (STAT3), the most extensively studied member of the STAT family, exhibits hyperactivation in a majority of human cancers and is generally associated with poor clinical prognosis, highlighting its significance in cancer." (PMID 39940889, 2025). "Moreover, copper depletion in cancer cells inhibits the phosphorylation of STAT3, epidermal growth factor receptor (EGFR), AKT and GSK3β." (PMID 39744687, 2025). "Additionally, inhibiting STAT3 activity can limit cancer cell proliferation and invasion while inducing apoptosis." (PMID 40350446, 2025). "Thus, the MVP ribonucleoprotein complex was shown to inhibit cancer cell proliferation and survival via the inhibition of STAT3 signaling and enhancement of HIF1α." (PMID 40243914, 2025). "Similarly, IL-6 directly promotes cancer cell proliferation by activating signal transducer and activator of transcription 3 (STAT3), which drives cell cycle progression." (PMID 40648921, 2025). "This further suggests that DUSP13B may have a negative regulatory relationship with p‐STAT3, and further verification of this finding is needed in other types of cancer tissues in future studies." (PMID 39721017, 2025). "Furthermore, the KRAS signaling pathway, IL6/JAK/STAT3 pathway, and IL-2/STAT5 pathway were strongly linked to STX7 expression in cancer." (PMID 40999361, 2025). "In BC, STAT3 and MYC play a role in the transcription of microRNAs (miRNAs) implicated in cancer." (PMID 41186627, 2025). "Thus, this research included in vitro and in silico studies to explore the effect of C. lanceolatus components on STAT3 inhibition in cancer." (PMID 40061959, 2025). "Chemokine CCL5 increases cancer stemness features, and STAT3 and PI3K/AKT activation." (PMID 40683954, 2025). "Consistent with previous studies showing that STAT3 could induce PD-L1 expression in various cancer cells, we found that cilengitide treatment enhanced the expression of PD-L1 in GBM cells." (PMID 40131864, 2025). "Therefore, because of their expected efficacy against cancer, STAT3 signaling blockers are of tremendous interest." (PMID 40217305, 2025).
cancer (continued). "Also, IL-17 has been shown to enhance angiogenesis by encouraging cancer cells to release vascular endothelial growth factor (VEGF) via the signal Transducer and activator of Transcription 3 (STAT3)/girdin-like protein (GIV) signaling pathway in NSCLC tissue." (PMID 41023740, 2025). "Numerous studies have demonstrated that STAT3 can effectively promote cancer progression in TNBC." (PMID 40830747, 2025). "Phosphorylated STAT3 (pSTAT3) enters the nucleus and binds to DNA sequences called gamma-activated sequences as a transcription factor, inducing the expression of genes involved in the development, progression, and/or immune evasion of cancer." (PMID 41104968, 2025). "Besides, irisin reversed IL-6-induced EMT process in OS cells via the STAT3/Snail signaling pathway, consequently suppressing cancer cell migration and invasion." (PMID 40909292, 2025). "Monogenic CVIDs with highest predisposition to cancer include the activated phosphoinositide 3-kinase delta syndrome (APDS), nuclear factor kappa B subunit 1 (NF-kB1) insufficiency, and signal transducer and activator of transcription 3 (STAT3) gain-of-function." (PMID 40925926, 2025). "Clarifying dietary Maca polysaccharides’ modulation of macrophage polarization and NRF2/STAT3 pathways against aflatoxin B1 toxicity and validating Chlorella vulgaris’ protective effects on NF-κB and caspase signaling in nicotine-induced cancer represent promising redox therapeutic strategies." (PMID 41009046, 2025). "STAT3 regulates the initiation and progression of human cancer through multiple mechanisms." (PMID 40166646, 2025). "However, in numerous cancer cell types, STAT3 exhibits constitutive activation and elevated expression levels." (PMID 41488475, 2025). "STAT3 is a transcription factor that is involved in a variety of biological processes such as cell proliferation and differentiation and angiogenesis, but is overactivated in most cancer cells." (PMID 40740310, 2025). "STAT3 is often constitutively activated in various cancers, including breast, lung, and hematological malignancies, with this aberrant activation typically arising from mutations, overexpression of upstream cytokine receptors, or dysregulation of related signaling pathways." (PMID 40918170, 2025). "Current evidence suggests that while pS727 plays a pivotal role in mitochondrial STAT3 translocation and cancer progression, the excessive inhibition of pS727 could lead to undesirable toxic effects in clinical trials." (PMID 40075607, 2025). "Interleukin 6 (IL-6), enriched in cancer-associated adipocytes, and lipolysis-derived free fatty acids (FFAs) released from adipocytes, amplify ANGPTL4-mediated glycolysis and metastasis through activation of STAT3 and PPARα pathways in TNBC cells." (PMID 40616161, 2025). "Therefore, we aim to develop a novel and effective dual-targeting BRD4/STAT3 inhibitor to avoid the liability arising from monotherapy and combination therapy and provide a new option for cancer treatment." (PMID 40078291, 2025). "Our previous study also confirmed that the NF-κB/IL-6/STAT3 positive feedback loop plays a crucial role in inflammation and pro-survival and might be an essential link between inflammation and cancer." (PMID 40129988, 2025). "Furthermore, curcumin modulates key signaling pathways, activating MAPK (mitogen-activated protein kinase) and inactivating STAT3 (signal transducer and activator of transcription 3), a pathway crucial for cancer cell survival." (PMID 40227413, 2025). "Aberrant STAT3 activation performs a serious role in the advancement of several cancer types." (PMID 41068541, 2025).